STAT3 (signal transducer and activator of transcription 3)
Diseases named in the same sentence as STAT3 in open-access papers (continued):
Sharing a sentence is not in itself a finding about the gene and the disease.
acute kidney injury (37 papers, 2015 to 2025). Sudden and sustained deterioration of the kidney function characterized by decreased glomerular filtration rate, increased serum creatinine or oliguria. "This suggests that the PI3K-AKT pathway mediated by STAT3 inhibition is specific to acute kidney injury." (PMID 39367511, 2024). "This study investigated the role of STAT3 in LPS-induced acute kidney injury (AKI) and its prolonged pathophysiological effect." (PMID 39367511, 2024). "We and others have found that STAT3 activation leads to the progression of acute kidney injury and kidney fibrosis." (PMID 39335615, 2024). "TOFA ameliorates lipopolysaccharide-induced acute kidney injury by blocking the JAK-STAT1/STAT3 signaling pathway." (PMID 36737780, 2023). "According to reports, curcumin exhibits the attenuation of inflammation by modulating the NF-κB and JAK2/STAT3 signaling pathways in response to acute kidney injury." (PMID 37627579, 2023). "It reported that activation of JAK/STAT3 signaling was involved in cisplatin-induced acute kidney injury." (PMID 36692085, 2023). "Although it has been previously reported that IL-6 stimulates STAT3 phosphorylation in acute kidney injury, the mechanism of IL-6 in the STAT3/NF-kB signaling pathway remains to be investigated." (PMID 33995063, 2021). "miR-155-5p enhances oxalate- and calcium-triggered kidney oxidative stress injury by repressing matrix gla protein (MGP) expression and aggravating both inflammation and apoptosis in acute kidney injury tissues via the Jak2/Stat3 pathway." (PMID 33457405, 2020). "Similarly, IRI increased STAT3 in kidneys, and pharmacologic inhibition of STAT3 with Stattic attenuated acute kidney injury and decreased macrophage infiltration in mice." (PMID 36982554, 2023). "Indeed IL-6 trans-signaling by the recombinant IL-6/sIL-6R fusion protein, Hyper-IL-6 (HIL-6) can strongly upregulate STAT3 phosphorylation in the kidney and largely prevent ROS-mediated acute kidney injury (AKI)." (PMID 34055865, 2021). "Studies have shown that targeting VEGFA can regulate the STAT3 signaling pathway to inhibit inflammation and oxidative stress, thereby delaying the progression of hyperuricemia-induced chronic dilatation renal fibrosis, improving renal failure, and reducing serum UA levels." (PMID 38257230, 2024). "Interestingly, STAT3 activation, despite its acute protective myocardial effects after IR, has also been strongly implied in atrophying skeletal muscle in experimental models of cancer cachexia or renal failure." (PMID 29872405, 2018). "In an acute kidney injury model, IL - six promotes ferroptosis by reducing glutathione (GSH) in renal tubular cells through the activation of the JAK2/STAT3 axis." (PMID 40371332, 2025). "In a septic acute kidney injury mouse model, curcumin showed anti-inflammatory capacity and attenuation of apoptosis by JAK2/STAT3 and NF-κB signaling pathway inhibition, resulting in increased levels of Bcl-2 and decreased levels of Bax and caspase-3." (PMID 39203857, 2024). "Similarly, α7nAChR reduced the inflammatory response by modulating NF-κB (p65) and IL-6/JAK2/STAT3/SOCS3 signals in acute kidney injury (AKI) model." (PMID 37429998, 2024). "Using a cisplatin-induced acute kidney injury (CAKI) mouse model, we found that inhibition of JAK/STAT3 significantly mitigates cisplatin nephrotoxicity with a reduced level of serum BUN and creatinine as well as proximal tubular distortion." (PMID 36692085, 2023). "Hence, here, we suggested a novel strategy for AKI management using STAT3 inhibitors as the inhibition of STAT3 signaling alleviated the progression of acute kidney injury to chronic kidney disease through anti-apoptosis." (PMID 36246123, 2022). "However, STAT3’s role in acute kidney injury (AKI), particularly in macrophage migration, and in chronic kidney disease (CKD) through fibrosis development, remains unclear." (PMID 39367511, 2024).
acute kidney injury (continued). "It was shown that STAT-3 activation in mesangial cells alters the immune response, promotes mesangial cell proliferation and glomerulonephritis in diabetic nephropathy, human immunodeficiency virus (HIV)-associated nephropathy (HIVAN), toxic nephropathy and acute kidney injury (AKI)." (PMID 36374911, 2022). "Moreover, HO-2 may exert a protective effect from acute kidney injury (AKI) at least in part mediated by inhibition of phosphorylated STAT3-dependent signaling." (PMID 32486245, 2020).
malignant glioma (36 papers, 2009 to 2024). A grade III or grade IV glioma arising from the central nervous system. "CD109 associates with STAT3 phosphorylation and poor survival of malignant gliomas." (PMID 33986188, 2021). "Efforts to clinically inhibit STAT3 are underway, including a phase I clinical trial of a small-molecule inhibitor targeting JAK2 activity, WP1066, to suppress STAT3 function in recurrent malignant glioma." (PMID 38892466, 2024). "A positive correlation between MGMT level and phosphorylated STAT3 has been reported in human malignant gliomas, which is consistent with our report." (PMID 37298405, 2023). "Overactivation of STAT3 is frequently observed in malignant gliomas and correlated to the mesenchymal subtype of GBM, a particularly aggressive and treatment-resistant molecular subgroup of these tumors." (PMID 35053502, 2022). "JAK inhibition, although historically employed in the treatment of myeloproliferative disorders, represents another avenue of STAT3 pathway targeting in malignant glioma." (PMID 33498872, 2021). "Lastly, there has been considerable interest in developing novel pharmacologic inhibitors of NF-κB and STAT3 for the treatment of malignant gliomas." (PMID 26755664, 2016). "In fact, clinical trials are ongoing to target PDGFR amplification or Stat3 activity in patients with malignant gliomas." (PMID 27344175, 2016). "The results show that the abnormal activation of STAT3 plays an important role in the occurrence and development of malignant glioma." (PMID 26788112, 2015). "WP1066 has been shown to significantly inhibit growth of malignant glioma xenografts by blocking STAT3 activation and the subsequent induction of proliferation-related genes." (PMID 25955030, 2015). "In malignant glioma, the expression of activated STAT3 can increase the expression of vascular endothelial growth factor (VEGF)." (PMID 26788112, 2015). "High expression and activation of STAT-3 and overexpression of its downstream target c-myc are well known to be pathophysiological mechanisms in malignant glioma." (PMID 26485029, 2015). "STAT3 is generally overexpressed in cancers including malignant gliomas and plays an important role in negative regulation of antitumor immunity." (PMID 25009822, 2014). "STAT3 inhibition was shown to reverse the immunosuppressive environment in malignant gliomas and to promote the efficacy of ACT in a murine glioma model." (PMID 25009822, 2014). "Priebe and his colleagues synthesised WP1066 by modifying the structure of AG490, and WP1066 has been shown to inhibit STAT3 activity and to have a potent antitumour effect on malignant glioma cells, both in vitro and in vivo." (PMID 20461084, 2010). "The constitutive activation of STAT3 coexists with EGFR expression in 27.2% of primary high-grade/malignant gliomas." (PMID 20113523, 2010). "Hypoxia-induced protective autophagy via activation of p-STAT3-miR-155-3p-CREBRF-CREB3-ATG5 pathway could accelerate malignant glioma progression." (PMID 35541892, 2022). "It was demonstrated that T-oligos could remarkably promote LC3-ll levels in malignant glioma cells and active autophagy by inhibiting mTOR and STAT3 signaling pathways, and then lead to the autophagic death of tumor cells." (PMID 36501031, 2022). "We conclude that the percent of PBMCs displaying p-STAT-3 may be increased in malignant glioma patients." (PMID 19900287, 2009). "We and others have shown that p-STAT-3 is upregulated in the vast majority of malignant gliomas." (PMID 19900287, 2009). "Therefore, we hypothesized that the percent of peripheral blood mononuclear cells (PBMCs) displaying p-STAT-3 may be increased in malignant glioma patients." (PMID 19900287, 2009). "The challengeable targets for the treatment of malignant gliomas can be TGF-β, Tregs, and signal transducer and activator of transcription 3 (STAT3)." (PMID 25009822, 2014).
malignant glioma (continued). "To ascertain if PBMC expression of p-STAT-3 correlated with the degree of immune suppression, we directed our attention specifically to the Treg fraction in the CD4 compartment since the Treg fraction is elevated in patients with malignant glioma patients." (PMID 19900287, 2009). "Notably, the novel orally administered STAT3 inhibitor (WP1066) has been developed with excellent blood–brain-barrier penetration and a Phase I Trial (NCT01904123) is currently ongoing against recurrent and malignant glioma." (PMID 34302498, 2021). "Further, in malignant glioma cells, it has shown that IL-4 induces aberrant STAT3 activation, but not STAT6 activation, suggesting that a defective STAT6 signal might drive STAT3 activation." (PMID 31530290, 2019). "It has been reported that inhibition of STAT3 stimulates autophagic flux and induces autophagic rather than apoptotic cell death in malignant glioma, suggesting that STAT3 may be the main factor responsible for CPX-induced autophagic death rather than apoptosis in GC cells." (PMID 36443287, 2022). "According to the multivariate role of STAT3 in the immune escape too, interestingly SR141716 lead also to the functional and selective expression of MICA/B on the surface of responsive malignant glioma cells, but not on NHA." (PMID 26008966, 2015).
acute pancreatitis (34 papers, 2019 to 2025). An acute inflammatory process that leads to necrosis of the pancreatic parenchyma. "USP25 facilitated pro-inflammatory factor production and tight junction impairment via STAT3 pathway, causing exacerbated acute pancreatitis (AP) and AP-related organ injury." (PMID 37814350, 2023). "Moreover, other JAK/STAT family members, such as JAK2/STAT3 pathway, mediated adhesion molecule expression in a rat model of severe acute pancreatitis-associated lung injury and in endothelial cells." (PMID 34638942, 2021). "In contrast, the renoprotective effect of curcumin in AKI caused by lipopolysaccharide (LPS) or severe acute pancreatitis may be associated with inflammation reduction mediated by suppression of JAK2/STAT3 signaling pathway." (PMID 33928100, 2021). "In a rat model of liver injury associated with severe acute pancreatitis, the inhibitor AG490 of JAK2 effectively reduced the serum levels of TNF, IL-6, and IL-18 by blocking excessive JAK2 and STAT3 activation." (PMID 38543164, 2024). "This indicates that Glycyrrhizin can inhibit the ERK1 and STAT3 signaling pathways, thereby affecting downstream Akt signaling and improving acinar cell death in acute pancreatitis." (PMID 38280993, 2024). "Several rodent studies have shown protective effects of ERK inhibition in experimental acute pancreatitis, whereas the role for STAT3 activation is less clear." (PMID 35408908, 2022). "In view of this, the role of JAK2/STAT3 signaling pathway in cerulein-induced acute pancreatitis was important to explore." (PMID 35042436, 2022). "What is more, one previous study evidenced that JAK2/STAT3 signaling pathway played a central role in the advancement of acute pancreatitis." (PMID 35042436, 2022). "The increase of p-STAT3 activates the inflammatory signaling pathway, thereby increasing the release of inflammatory factors, which damages tight junctions and aggravates acute pancreatitis." (PMID 35096833, 2021). "We furtherly explored the underlying mechanisms and acquired the results indicating that ES promotes apoptosis in STC-induced acute pancreatitis via downregulating the ERK/STAT3 signaling pathway." (PMID 34422214, 2021). "In summary, Escin Sodium pretreatment improves the prognosis of acute pancreatitis induced by STC via inducing apoptosis mediated by the ERK/STAT3 signaling pathway." (PMID 34422214, 2021). "In view of this, we wondered whether FXYD5 downregulation could inhibit the inflammatory response in acute pancreatitis via regulating JAK2/STAT3 pathway." (PMID 35042436, 2022). "Conversely, in vivo IL-10 attenuated the increased BBB permeability in rat models of severe acute pancreatitis by reducing brain microvascular endothelial cells apoptosis through a signal transducer and activator of transcription 3 (STAT3) pathway mediated downregulation of claudin-5 expression." (PMID 34983592, 2022). "We first found that ES could reduce the level of p-ERK and p-STAT3 consistently in vivo in STC-induced acute pancreatitis." (PMID 34422214, 2021). "Reg3a has been shown to regulate keratinocyte proliferation and differentiation after skin injury via Reg-Extl3-PI3K-Cyclin D1 pathway, while Reg3g downregulates the Stat3-Socs signaling which may result in enhanced apoptosis in acute pancreatitis." (PMID 34926699, 2021). "Moreover, the expression of IL-10 may suppress acute pancreatitis, and notably, Sawada found that IL-10 and its downstream STAT3 pathway regulate the proliferation of cells infected with HTLV-1." (PMID 33556114, 2021). "Furthermore, hsa-miR-148a could inhibit autophagy through IL-6/STAT3 axis in AP in acute pancreatitis." (PMID 32149089, 2020). "Studies on severe acute pancreatitis (SAP) in rats have found that JAK2 and STAT3 protein expression levels were significantly increased following induction of SAP." (PMID 35590365, 2022).
acute pancreatitis (continued). "SAP contributes to hepatocyte injury during acute pancreatitis, and SAP-induced hepatocellular injury is consistent with the previous reports; the JAK2/STAT3 signaling pathway plays an important role on liver injury associated with SAP in the rat model." (PMID 34368363, 2021). "In rats with severe acute pancreatitis, curcumin was protective against acute renal injury by suppressing the JAK2/STAT3 pathway." (PMID 34434118, 2021). "Furthermore, our in vitro experiments have revealed that Glycyrrhizin exerts inhibitory effects on the ERK1/2, STAT3, and downstream p-AKT signaling pathways, leading to a remarkable amelioration of acinar cell death in acute pancreatitis." (PMID 38280993, 2024). "In severe acute pancreatitis induced acute lung injury, stellate ganglion block promoted the expression of SOCS5, inhibited the expression of miR-155-5p, and inhibited the activation of JAK2/STAT3 pathway." (PMID 38267898, 2024). "Although a previous study sporadically showed that DCQD could regulate inflammatory cytokines and intestine injury in rats with severe acute pancreatitis via JAK2/STAT3 signaling pathway, the potential mechanism of DCQD participating in AP through JAK2/STAT3 is not clear." (PMID 33927777, 2021).
pneumonia (34 papers, 2012 to 2025). An acute, acute and chronic, or chronic inflammation focally or diffusely affecting the lung parenchyma, caused by an infection in one or both of the lungs (by bacteria, viruses, fungi, or mycoplasma.). "The STAT3 cytokine signaling pathway is downstream of the NF-κB pathway, and dysregulated TNF levels cause hyperactivation of STAT3, which also correlated with severe pneumonia during respiratory ectromelia virus (ECTV) infection." (PMID 36851532, 2023). "AC larval migration caused fatal lung injury (pneumonia) during acute and early infection phases, along with significant activation of Stat3/IL-6 signaling." (PMID 35617354, 2022). "Majority of our patients with STAT3 rare variants presented with recurrent skin abscesses (77.7%) and pneumonia (62.9%) which were seen in 73 and 38% of the French cohort." (PMID 33717144, 2021). "MiR-4485 inhibited H1N1-induced severe pneumonia by suppressing STAT3 expression; the authors found that silencing STAT3 reversed the effects of miR-4485 downregulation on H1N1-induced cell injury." (PMID 39769350, 2024). "The immunological features include elevated serum IgE, eosinophilia, reduced neutrophil chemotaxis, Staphylococcus skin infections, and pneumonia along with reduced Th17 cells, memory B cells, and STAT3 phosphorylation." (PMID 39229272, 2024). "Apart from the classical manifestations of HIES like early-onset eczema, skin infections, pneumonia and elevated IgE, allergic manifestations including food allergies and asthma are more prevalent in DOCK8 deficiency than in STAT3 deficiency." (PMID 36140582, 2022). "Newborn rash, skin abscesses, chronic mucocutaneous candidiasis and pneumonia are highly specific of STAT3-HIES." (PMID 36140582, 2022). "Depleting the hepatic STAT3 and RelA ablated the acute-phase response induction and increased the mortality in a mouse pneumonia model." (PMID 30151394, 2018). "LIF is a prominent STAT3-activating cytokine that facilitates tissue protection during pneumonia and plays a similar airway protective role during RSV infection." (PMID 25277705, 2014). "Loss of function STAT3 Hyper IgE syndrome (LOF STAT3 HIES) is a rare inborn error of immunity characterized by a clinical triad of high serum IgE (>2,000 IU/mL), skin abscesses, and pneumonia." (PMID 39229272, 2024). "We hypothesized that a similar approach of simultaneous targeting of the virus and the STAT3 signaling pathway might also be effective in the IAV pneumonia model." (PMID 36851532, 2023). "Overall, we are the first to provide direct and systemic laboratory evidence of AC migration route in a nonpermissive host and report that infection with a high dose of AC larvae could result in acute and fatal pneumonia through Stat3/IL-6 signaling in mice." (PMID 35617354, 2022). "Overall, we confirmed that pneumonia in the host was mediated by the Stat3/IL-6 pathway and that blockade of Stat3/IL-6 signaling could significantly attenuate AC infection-induced pneumonia in the host." (PMID 35617354, 2022). "More importantly, we first reported that during the acute and early infection phases, AC larvae could induce mouse fatal pneumonia, with significant activation of Stat3/IL-6 signaling and enrichment of myeloid cells." (PMID 35617354, 2022). "Hepatic STAT-3 and RelA knock out increased the mortality in a mouse pneumonia model." (PMID 30473633, 2018). "Moreover, STAT3-dependent IL-1β expression in cDCs at least partially explains the IL-21-mediated pathologic response occurring during infection with pneumonia virus of mice." (PMID 26269257, 2015). "Our study reports the migration route of Angiostrongylus cantonensis larvae in non-permissive host mouse and discovers that the larvae could induce fatal pneumonia in mouse lung during acute and early infection phase characterized by activation of Stat3/IL-6 signaling." (PMID 35617354, 2022).